MMP7 (matrix metallopeptidase 7)
Diseases named in the same sentence as MMP7 in open-access papers (continued):
Sharing a sentence is not in itself a finding about the gene and the disease.
tumor (continued). "Thus, the WNT signaling pathway is activated, and the expression of WNT pathway-related proteins c-myc, snail, MMP2, MMP7 and MMP7 is increased, which enhances the ability of tumor metastasis and invasion." (PMID 38343637, 2024). "Notably, CD14+APOE+ cells were predominantly located in areas with high MMP7+ tumour cells, suggesting a strong co‐localisation pattern between MMP7+ tumour cells and CD14+APOE+ cells." (PMID 39187937, 2024). "Despite the sharp increase in this subgroup, MMP-7 levels remained high in the LN-positive patients, suggesting that tumor cells producing MMP-7 might remain behind after RC and LND." (PMID 37175566, 2023). "Besides, more and more evidences support MMP7 as an oncogene involved in tumor cell proliferation, migration and apoptosis." (PMID 36936416, 2023). "Therefore, MMP-7 is involved in several tumor-supporting cellular processes, such as apoptosis, angiogenesis, and tumor-related osteolysis." (PMID 37175566, 2023). "Interestingly, the up-regulation of MMP7 was F. nucleatum-dose-dependent, suggesting that the more amount of F. nucleatum in the tumor, the more significant the expression of MMP7, and the stronger the effect of F. nucleatum to promote cancer cell metastasis." (PMID 37814323, 2023). "Furthermore, the expression of EMT genes and oncogenes, including Mmp3, Mmp7, Mmp8, Fn1, Vim, Foxc2, Ctnnb1, Lgr5, Axin2, cMyc, Ccnd1, and Yap1, was significantly high in the tumor of cohoused Nlrp12–/– compared with WT mice." (PMID 37581937, 2023). "Another important molecule that is downregulated in drug‐treated KPC tumour tissue is MMP7." (PMID 38131168, 2023). "In addition, we detected a significant decrease in serum MMP-7 levels in patients with high preoperative MMP-7 concentrations, suggesting tumor cells were the main source of serum MMP-7." (PMID 37175566, 2023). "Furthermore, the expression ofβ-catenin and c-myc in the Wnt/β-catenin signalling pathway was increased in the RBBP5 knockdown group in xenogeneic tumor tissues of nude mice, and N-cadherin and MMP-7 in EMT also increased." (PMID 36866240, 2023). "MMPs are extracellular proteases that target cytokines and receptors; moreover, one member of the MMP family (MMP7) is widely overexpressed in approximately 80% of CRC cases, and is associated with tumor neovascularization, invasion, and distant lymph node metastasis." (PMID 36672201, 2023). "The abnormal excitation of the pathway due to genetic mutation or increased stability can activate the abnormal expression of downstream target genes, including, c-Myc, Cyclin, and MMP-7, which can lead to cell proliferation, inhibition of cell apoptosis, and tumor formation." (PMID 37666882, 2023). "Therefore, MMP7 is expected to become a potential biomarker for evaluating tumor prognosis and a new target for tumor therapy." (PMID 36936416, 2023). "Knockdown of MMP7 gene can inhibit tumor proliferation, migration and reduce drug resistance." (PMID 36936416, 2023). "Additionally, others have shown that VEGFA-mediated development of CRC tumor angiogenesis was impeded by inhibition of MMP7." (PMID 36672201, 2023). "Accordingly, we observed that MMP-7 was overexpressed in tumor samples, compared to normal skin." (PMID 36518899, 2022). "Since we observed induced drug efflux activity correlating with increased MMP7 expression, we asked whether enforced MMP7 expression alone can promote both drug efflux activity and tumor progression." (PMID 32761892, 2022). "Therefore, we have examined the functional consequence of MMP7 expression in regulating the drug resistance and tumor metastasis." (PMID 32761892, 2022). "However, MMP7 OE cells showed a decrease in s.c. tumor growth, which was increased in response to 17AAG treatment." (PMID 32761892, 2022).
tumor (continued). "Hence, the potential correlation between the expression of MMP7 and the infiltration levels of CAFs/tumor-infiltrating immune cells across all TCGA cancers using EPIC, MCPCOUNTER, XECLL, TIDE, CIBERSORT, CIBERSORT-ABS, and QUANTISEQ methods was explored." (PMID 35785154, 2022). "In addition, MMP7 is also considered to be involved in tumor metastasis and inflammatory cascades reaction." (PMID 35785154, 2022). "In particular, PRL-3 promotes tumor cell invasion by upregulating MMP-7 in human CRC." (PMID 35574414, 2022). "In the process of tumor growth, MMP-7 plays the role in tumor invasion and metastasis." (PMID 36119495, 2022). "In a PANC1 orthotopic xenograft mouse model, a single injection of hAFMSCs showed significant tumor growth inhibition with evidence of the modulation of cell cycle and pro-apoptotic regulatory genes and various genes involved in matrix metallopeptidase 7 (MMP7) signaling-triggered EMT process." (PMID 35659367, 2022). "MMP-7 acts in tumor cell metastasis by activating the ERK 1/2 and JNK 1/2 signaling pathways." (PMID 36776395, 2022). "However, the serum MMP7 levels in the PANC1 tumor-bearing mice that received hAFMSCs transplantation were significantly reduced (67.38 ± 21.28 pg/ml; hAFMSCs)." (PMID 35659367, 2022). "On the other hand, the products of the proteolytic degradation by MMP-7 may generate bioactive molecules with potential effects on tumour progression." (PMID 35327500, 2022). "Through tumor cytology examination, MMP-7 was highly expressed in patients with tumor." (PMID 35242806, 2022). "It downregulated the MMP-7 expression and hindered tumor development and tumor cell invasion." (PMID 35990343, 2022). "BCAR4 overexpression can promote tumor growth by modulating miR-2276/MMP7 axis." (PMID 34937497, 2022). "The tumor volume comparison between different s.c. injected animals before sacrificing indicates that 17AAG treatment significantly increases the s.c. tumor volume in MMP7 OE cells." (PMID 32761892, 2022). "However, MMP7 OE cells showed tumor metastasis in the lung, which is in addition to the kidney and spleen." (PMID 32761892, 2022). "MMP7 is upstream of MMP9 and MMP2 that are extensively implicated in tumor metastasis." (PMID 32761892, 2022). "By extrapolating these studies, we asked whether there is any cross‐talk between Hsp90 and MMP7 in regulating the drug resistance and tumor metastasis." (PMID 32761892, 2022). "This decrease suggests that circulating MMP-7 levels directly originate from the tumour tissue." (PMID 35327500, 2022). "For autoantibodies against MMP-7 and Hsp70, there are relatively few studies on tumor prognosis." (PMID 34336006, 2021). "The abnormal excitation of the pathway due to genetic mutation or increased stability can activate the abnormal expression of downstream target genes, including Cyclin, C-Myc, and MMP-7, which can lead to cell proliferation, inhibition of cell apoptosis, and tumor formation." (PMID 34421589, 2021). "We further observed an overall negative association between NME4 and tumor invasion markers like genes encoding matrix-degrading proteases (MMP7, ADAM17) and actin cytoskeleton remodelers (ROCK1, ROCK2, LIMK2, CFL2, MYO5A)." (PMID 34674701, 2021). "Finally, matrix metalloproteinase-7 (MMP7), a member of the zinc-dependent proteolytic enzymes family, degrades the extracellular matrix favoring tumor invasion, metastasis and angiogenesis by matrix-bound VEGF releasing." (PMID 34067294, 2021). "Moreover, tumor tissues obtained from patients with high-risk scores tended to express high level of prognostic genes (AGT, SERPINH1 and MMP7)." (PMID 34215253, 2021). "Furthermore, some oncogenic genes like EGFR, CDK6, YAP1, and MMP7 were amplified in the TP53INP2-low patients while some tumor suppressor genes including CDKN2A, KLF6, and PTEN were deleted." (PMID 33897760, 2021). "A major ratio of MMP-7 expression in tumor cells has been reported." (PMID 34944846, 2021).
tumor (continued). "On the other hand, the significant downregulation of VEGF and MMP-7 suggested that compounds 2 and 5 also exhibited good effects in suppressing tumor invasion, angiogenesis, and metastasis, which need to be further verified via functional experiments in vitro and in vivo." (PMID 34638708, 2021). "DKK1 expression was positively correlated with tumor volume as well as MMP-7 expression." (PMID 34093545, 2021). "Among MMPs, matrix metalloproteinase 7 (MMP-7, matrilysin) has emerged as an important target for development of next generation cancer therapeutics, due to its association with the clinical behavior of multiple tumor types." (PMID 33918254, 2021). "We conclude that MMP-7 plays a key functional role in PCa cell transition from a cohesive, indolent phenotype to a dyscohesive, migratory phenotype favoring production of circulating tumor cells and metastasis to bone." (PMID 33809984, 2021). "MMP-7 is secreted by epithelial cells, macrophages, myolytic myocytes and tumour cells themselves." (PMID 33916127, 2021). "Interestingly, it has been also suggested that MMP-7 can contribute to the expansion of tumor stroma, stimulating the proliferation and migration of human colonic fibroblasts." (PMID 33946534, 2021). "MMP-7 cleaves Fas ligand and removes it from the cell surface, which therefore cannot stimulate the Fas death receptor, involved in the activation of innate apoptosis, leading to the survival of tumor cells." (PMID 34912809, 2021). "In addition, secreted forms of MMP-7 can modify several pathophysiological functions such as tumor metastasis and inflammation." (PMID 34769248, 2021). "Inspired by this, we assumed that MPC1 could mediate tumor cell motility through affecting MMP7 activity, cell-cell contacts, and EMT." (PMID 32851100, 2020). "In addition, our data suggest the importance of tumor–stroma interaction in the regulation of MMP-7." (PMID 33396213, 2020). "Likewise, the matrix metalloproteinase-7 (MMP7) gene, which is normally responsible for tissue remodeling, is overexpressed in cases of tissue invasion as well as tumor formation." (PMID 33112566, 2020). "The different roles of MMP24 and MMP7 in cancer progression could be due to the different ECM types surrounding the tumor, which control angiogenesis for metastasis and growth of cancer cells." (PMID 32093160, 2020). "Based upon these reports, it is suggested that MMP7 is an important regulator of tumor formation." (PMID 32325664, 2020). "MMP7 promotes tumor growth in many different cancers, including breast cancer." (PMID 32483202, 2020). "It remains unclear why the role of MMP24 in tumor aggressiveness is opposite to that of MMP7 and their roles are cancer type-dependent." (PMID 32093160, 2020). "MMP-7 was expressed by the tumor cells and, in many cases, focally localized to tumor cells at the tumor–stroma interface, while in some cases, a weak MMP-7 expression could be observed with a rather homogeneous distribution within the tumor." (PMID 33396213, 2020). "We demonstrated that both GP73 and MMP-7 were upregulated in primary tumor tissues, and, critically, MMP-7 was highly expressed in and near high GP73 expression cells, which suggested that GP73 was involved in the secretory process of MMP-7 from cytosol to extracellular spaces." (PMID 31591387, 2019). "Moreover, GP73 was correlated positively with MMP-7 in both tumor tissues and adjacent liver tissues (R2 = 0.3094)." (PMID 31591387, 2019). "Moreover, β-catenin can increase the transcription of downstream β-catenin signaling pathway-related genes, including VEGF, MMP2, and MMP7, thereby leading to tumor cell proliferation and metastasis." (PMID 31004081, 2019). "MMP-7 is also expressed in the invasive front of colon cancer and correlates with tumor stage." (PMID 31344926, 2019). "For example, MMP-3 and MMP-7 interact in vivo with osteopontin at tumor sites and may be related to the angiogenic process during tumor development." (PMID 31921634, 2019).
tumor (continued). "Excessive expressions of N-cadherin, MTA1, MMP-2, and MMP-7 also facilitate tumor metastasis." (PMID 31189744, 2019). "MMP-7 degrades laminin and type IV collagen to facilitate tumor invasion." (PMID 29731961, 2018). "MMP-7 and MMP-9 are the main proteases of zinc-dependent endopeptidases and participate in extracellular matrix degradation, which is associated with the movement of tumour cells." (PMID 29466986, 2018). "Although FAS has been shown to be shed by MMP-7 in tumour cells, and addition of recombinant MMP-7 to hVSMCs did increase levels of sFAS (WRE unpublished data), we were unable to inhibit sFAS production with adenoviral overexpression of TIMP-1 or -2 which are potent inhibitors of MMP-7." (PMID 29617412, 2018). "Moreover, we demonstrated that CTHRC1 promoted tumour invasion by regulating MMP7 and MMP9 expression, which is mediated by the AP-1/c-Jun and NF-κB pathways, respectively." (PMID 29631554, 2018). "A percentage of 90% of the tumours expressed MMP-7 and MMP-25." (PMID 30539028, 2018). "Moreover, lycopene suppresses tumor cell invasion mediated by leptin as proteomic assays revealed that lycopene exposure significantly decreased expression levels of MMP7 and thereby reduce the tumor cells invasion capacity." (PMID 30487390, 2018). "In the present study, two genes ITGA2 and MMP7 were screened from DEGs as hub genes by using a series of bioinformatics methods, and they could discriminate normal samples and tumor samples." (PMID 30428899, 2018). "Secreted MMP‐7 may modify the tumor microenvironment by stimulating stromal cell migration and invasion." (PMID 29845775, 2018). "In addition, β-catenin can interact to the DNA binding protein TCF / LEF complex and regulate the expression of C-myc, C-jun, MMP7, and cyclinD and thus affect cell proliferation and metastasis of tumor cells." (PMID 30046596, 2018). "To further explore the role of Wnt-signaling pathway in regulating the EMT process induced by H. parasuis, we evaluated the function of three Wnt target genes, MMP7, COX2 and PAI-1, which have been proved to be associated with cell structural change and the process of EMT in some tumor cells." (PMID 30258822, 2018). "Moreover, ARF regulates tumor microenvironment through MMP7 (matrix metalloproteinase-7) nuclear translocation." (PMID 29185453, 2017). "Mangiferin considerably decreased tumor proliferation, weight, and volume, and enhanced apoptosis, as well as also decreased the expression levels of MMP-7, MMP-9, active β-catenin, vimentin, while increasing the expression of E-cadherin in in vitro MDA-MB-231 xenograft mice." (PMID 28464819, 2017). "MMP-7 has been considered as a metastatic marker and survival predictor in RCC patients; inhibition of MMP-7 expression and function in tumor cells could be one of the most powerful strategies in metastatic RCC therapy." (PMID 29234409, 2017). "In this study, PLCD1 negatively regulated pGSK-3β, active-β-catenin and MMP7, suggesting for the first time that the β-catenin signalling pathway may be involved in the anti-tumour activity of PLCD1." (PMID 28423710, 2017). "In addition to enhancing tumor invasion and metastasis directly, MMP-7 exerts indirect effects through the activation of MMP-2 and MMP-9." (PMID 27271600, 2016). "These tumor promoting functions of MMP7 are in good accordance with our clinical results and may indicate that a high abundance of serum MMP7 is a surrogate marker for a more aggressive tumor type." (PMID 27431388, 2016). "Additionally, TAMs also synthesize the elevated levels of MMP-7, which can stimulate endothelial cell proliferation and migration to support tumor angiogenesis, thus providing energy for tumor cell proliferation." (PMID 26831659, 2016). "Other studies have confirmed that MMP-7 shows proteolytic activity, participates in cell dissociation through disruption of tight junction structures, determines tumor dissociation from the primary tumor, and stimulates cancer cell invasion." (PMID 27429508, 2016).
tumor (continued). "In addition, the expression of MMP-7 in tumor cells differed statistically significantly from that noted in the peritumoral stroma (p = 0.005)." (PMID 27429508, 2016). "In turn, MMP-7 may lead to the degradation of the tumor stroma, decay of current vessels, and the inhibition of neovascularization." (PMID 27429508, 2016). "Furthermore, statistical analysis showed a significant difference between the expressions of MMP-2 and MMP-7 in normal and tumor tissues (p = 0.0001)." (PMID 27429508, 2016). "For MMP7 we could observe significant differences in the expression level regarding gender (p = 0.049), age (p = 0.013) and tumor site (p < 0.001)." (PMID 27431388, 2016). "Notably, degradation of perlecan by MMP-7 completely reversed its ability to trigger PCa cell clustering, leading to tumor dyscohesion and favoring a migratory single cell phenotype." (PMID 26862737, 2016). "Indeed MMP7 expression levels resulted enriched in tumour with high grade (tumour grade 3) and in patients, which encountered recurrence within 3 years from the primary tumour onset." (PMID 25596746, 2015). "Interestingly, MMP7 can enhance the growth rate of normal mammary epithelial cells and promote tumor formation in vivo." (PMID 26008979, 2015). "Furthermore, tumor progression leads to local tissue hypoxia, and thus the secretion of MMP-7 mediated angiogenic factors is increased." (PMID 29201696, 2015). "Conversely, MMP7 and OPN expression tended to be associated with the tumor tissue." (PMID 26517682, 2015). "Overall, studies of KAI1/CD82, CD44, MMP7 and β-catenin in relation to tumor metastasis indicate that these molecules are involved in the process of tumor progression through regulating the intercellular adhesion; However, there are few studies on the interaction between them." (PMID 26408312, 2015). "In addition to laminin-111, tumor cells growing alone secreted laminin-5, perlecan, MMP-7, TIMP-1 and CD44." (PMID 25885552, 2015). "The results suggest that MMP7 over-expression may be one of the mechanisms by which PKP3 loss leads to increased cell invasion and tumor formation." (PMID 25875355, 2015). "In addition to extracellular matrix degradation, MMP-7 enhances tumor progression by inhibiting apoptosis and reducing cell adhesion of cancer cells." (PMID 26699938, 2015). "Matrix metalloproteinase 7 (MMP-7) promotes tumor invasion and metastasis in several cancers." (PMID 25588786, 2015). "In contrast, the tumor controls MMP7 and OPN were clearly expressed in the cancerous liver samples." (PMID 26517682, 2015). "In contrast, MMP7 staining was more pronounced in the tumor center relative to the invasive front." (PMID 26652716, 2015). "However, when tumor cells became resistant to metformin after long-term and high-dose inducement by metformin, MMP7 and DCN expression was restored again, implying that the dosage of metformin should be limited in a low level." (PMID 25909163, 2015). "Moreover, this protein increased the transcription of target genes, including c-myc, cyclinD1, VEGF, and MMP7, by interacting with the T cell factor/lymphoid enhancer factor, thereby leading to the proliferation and metastasis of tumor cells." (PMID 24454854, 2014). "MMP-7 showed a significant decrease in expression levels during tumour evolution." (PMID 26019601, 2014). "In the light of this suggestion our data are interesting, as they indicate that MMP-7 could possibly serve as a predictive marker of tumour invasiveness in OSCC." (PMID 26019601, 2014). "Alternately, MMP-7 had increased expression in tumor tissue as compared to stroma (p < 0.001)." (PMID 25483099, 2014). "Furthermore, UPK1A inhibits the nuclear translocation of β-catenin and can serve as an antagonist to matrix metalloproteinase 7 (MMP7), thereby playing a prominent role in tumor suppression." (PMID 24698999, 2014).